ZNF561-AS1 (ZNF561 antisense RNA 1)
Synonyms: C19orf82
Gene: Long non-coding RNA gene on chromosome 19 (9,620,993 to 9,674,662, forward strand). Ensembl gene ENSG00000267106.
Diseases named in the same sentence as ZNF561-AS1 in open-access papers:
ZNF561-AS1 is named in the same sentence as 1 disease in open-access papers, as found by Europe PMC text mining. Sharing a sentence is not in itself a finding about the gene and the disease.
ZNF561-AS1 shares sentences with these, for which no sentence is quoted: breast carcinoma (1 paper).